EGFR (epidermal growth factor receptor)
Diseases named in the same sentence as EGFR in open-access papers (continued):
Sharing a sentence is not in itself a finding about the gene and the disease.
lung cancer (continued). "Besides, a retrospective cohort analysis including 285 lung cancer patients reveals that the EGFR mutations group has a better median overall survival of 20.0 months than that of 11.0 months in the non-mutated group (P-value: 0.007)." (PMID 33506873, 2021). "Additionally, combined treatment with afatinib and suberoylanilide hydroxamic acid (SAHA), a histone deacetylase (HDAC) inhibitor, evoked proapoptotic autophagy in EGFR T790M-mutated lung cancer cells." (PMID 34294686, 2021). "In lung cancer with EGFR mutations, ERK signaling is expected to be constitutively activated." (PMID 33486901, 2021). "For lung cancers, EGFR mutations have been linked with decreased cytotoxic T cell infiltration, whereas for colorectal cancers, KRAS mutations have been associated with increased marrow-derived suppressor cell infiltration and the subsequent decreased infiltration of cytotoxic T cells." (PMID 34108525, 2021). "In our previous study, by pharmacological exploration, we have found that tumor growth can be inhibited by cell cycle inhibition and antiangiogenesis with the VEGFA epidermal growth factor receptor CASP3 AKT1 CCND1 associated with the prognosis of lung cancer patients." (PMID 33628320, 2021). "This may be in part due to decreased migration, invasion, and metastasis of lung cancer cells and increased sensitivity to Erlotinib in EGFR mutated cells seen with knockdown of SALL4." (PMID 34573282, 2021). "Several clinical trials have been performed to determine whether adjuvantepidermal growth factor receptor (EGFR) tyrosine kinase inhibitors (TKI) improveoutcomes in early-stage EGFR-mutated lung cancer." (PMID 34104821, 2021). "The first was the cobas® epidermal growth factor receptor (EGFR) mutation test from Roche Molecular Diagnostics which uses cfDNA in blood to detect the EGFR gene mutation to guide clinical decision-making in lung cancer." (PMID 34873529, 2021). "Erlotinib is highly effective in lung cancer patients with EGFR mutations." (PMID 33188726, 2021). "Previous studies in mouse models have reported that activation of the oncogenic EGFR pathway enhances the susceptibility of lung cancer to PD-1 blockade, suggesting that the combination of PD1 blockade with EGFR TKIs may be a promising therapeutic strategy." (PMID 34834454, 2021). "Gain-of-function mutations in EGFR play a major role in lung cancer malignancy." (PMID 33889302, 2021). "It is known that in EGFR mutation-positive lung cancer, T790M-positive cells are present at an incidence rate of 79.9%, albeit at a low frequency when analyzed by an ultrasensitive method (0.009% to 26.9%), even before EGFR-TKI treatment." (PMID 34831415, 2021). "Patients with non‐small cell lung cancer (NSCLC) harboring activating EGFR mutations are sensitive to epidermal growth factor receptor‐tyrosine kinase inhibitors (EGFR‐TKIs) but inevitably develop resistance to the inhibitors mostly through acquisition of the secondary T790M mutation." (PMID 33471376, 2021). "Moreover, KRT19 mRNA was significantly associated with the presence of SCC, EGFR wt lung cancer, higher stage and shorter survival time of lung cancer patients." (PMID 33442422, 2021). "This was not the case for wild-type EGFR, suggesting that PD-L1 expression is increased by EGFR signaling conferred by activating EGFR mutations and the promotion of immune escape in lung cancer via increased PD-L1 expression through resistance to EGFR-directed small tyrosine kinase inhibitors." (PMID 33718186, 2021). "The study used a 2-step transfer learning strategy: first, the model was trained on a large lung cancer CT dataset (n=4106) along with epidermal growth factor receptor gene sequencing to learn associations between chest CT image and micro-level lung functional abnormalities." (PMID 33326405, 2021). "Lung cancer patients with EGFR mutation had lower percentage of CD8+ lymphocytes." (PMID 33859531, 2021).
lung cancer (continued). "The EGFR mutation rate in patients with lung cancer from Xuanwei is still controversial." (PMID 33928034, 2021). "In conclusion, our study showed that ANXA1 is a candidate for target therapy toward NSCLC and targeting ANXA1 may enhance the effects of EGFR-TKI in lung cancer cells with EGFR mutations." (PMID 34439260, 2021). "The integration of lung cancer screening algorithms into miRNA-dependent EGFR expression may be a useful tool for improving the screening specificity and lowering the mortality rate associated with lung cancer." (PMID 34830377, 2021). "Since an epidermal growth factor receptor (EGFR) activating mutation has been identified as one of the most common gene mutations in lung cancer, EGFR-tyrosine kinase inhibitors (EGFR-TKIs) became first-line molecular targeted therapies for EGFR-mutated NSCLC patients." (PMID 33967759, 2021). "The behavior of lung cancer cells is associated with miRNA-dependent EGFR expression." (PMID 34830377, 2021). "Although EGFR-sensitive mutations and other classical lung cancer gene mutations are rare, however, CYLD may be a new therapeutic target for PPLELC." (PMID 34760925, 2021). "Forty-one patients (34%) were found to have epidermal growth factor receptor (EGFR)-mutated lung cancer, while 65 had wild type EGFR tumors (54%); mutational status was unknown in the remaining 14 patients (12%)." (PMID 33837261, 2021). "In this study, we investigated whether SB exerted anticancer activities in EGFR TKI-resistant lung cancer cells and explored the underlying mechanism." (PMID 34068421, 2021). "Circulating tumor DNA (ctDNA), as a component of cfDNA of cancer patients, represents the mutation profile of tumor tissues, and the concordance between tissue and plasma ctDNA ranges from ~70% to ~90% for the detection of EGFR variants in nonsmall cell lung cancers." (PMID 34199654, 2021). "Interestingly, cinobufagin strongly inhibited the proliferation of lung cancer cells with wild-type or mutated EGFR expression." (PMID 34925034, 2021). "The causal relationship between EGFR mutation and lung cancer is then established." (PMID 35055327, 2021). "This is the first report of the detection of EGFR mutations of primary lung adenocarcinoma using ddPCR from prospectively collected sputum samples and compared it with an EGFR mutation in surgically resected lung cancer." (PMID 33757469, 2021). "The high fraction of patients harboring either EGFR and ROS1 positivity led authors to speculate that ROS1-rearranged and EGFR-mutated lung cancer may originate from a common precursor lesion." (PMID 34884672, 2021). "In this study, EGFR germline and somatic variants were retrospectively reviewed in 31,906 patients with lung cancer whose tumor tissues or peripheral blood samples were collected to perform a matched tumor-normal next-generation sequencing of 1,021 cancer-related genes." (PMID 34869019, 2021). "Actually, EGFR mutations are found in 40% of lung cancers, suggesting that EGFR might be identified as a selective target during cancer chemotherapy." (PMID 34576152, 2021). "The experience to date with HER2-targeting agents has revealed a degree of complexity with this amplified oncogene that sets it apart from oncogenes activated through gene mutation or fusion events such as EGFR or Alk in lung cancers, Bcr-abl in leukemias, or BRAF in melanomas." (PMID 33907275, 2021). "As researchers were starting to better understand the role of EGFR mutation as a driving force for some lung cancers, it was also being realized that an acquired resistance mutation, T790M, was responsible for many cases of treatment failure on first-generation agents." (PMID 33777559, 2021). "In conclusion, a small number of Chinese patients with lung cancer harbored unique and dispersive EGFR germline mutations, which may be related to their second primary carcinomas and cancer family history." (PMID 34869019, 2021).
lung cancer (continued). "Furthermore, we observed an increase in the clinical predictive performance for predicting the EGFR mutation status of lung cancer lesions after the kernel conversion to smooth (median AUC = 0.614, Z = 15.1, p < 0.001)." (PMID 34941646, 2021). "Furthermore, in lung cancer harboring EGFR mutations, findings indicate that exosomes represent suitable biomarkers for research into cancer and clinical application while also revealing new pathways in the discipline of nanomedicine." (PMID 33855679, 2021). "NCI-H1650, another lung cancer cell line, harbors an EGFR-activating mutation and has been described as IL-6-secreting, which we could confirm in our study." (PMID 34671021, 2021). "Therefore, in this study, we attempted to explore novel factors possibly associated with the EGFR-independent mechanisms of osimertinib in lung cancer." (PMID 34445227, 2021). "Furthermore, a phase Ib clinical trial of osimertinib combined with ramucirumab for lung cancer patients with EGFR mutations has been completed in Japan, and the safety for this combination treatment has been approved." (PMID 34575576, 2021). "Therefore, to assess the effect of ELF3 on lung cancer cell survival, we knocked down the expression of ELF3 by transfecting ELF3 siRNA into A549 (with K-Ras mutation) and H1975 (with EGFR L858R/T790M double mutation) lung cancer cells for 72 h." (PMID 34830169, 2021). "Of note, EGFR‐mutated lung cancer cells (eg, H1650 cell) are more sensitive to TKI, and we thus evaluated whether USP35 silence would sensitize H1650 cell to GFB chemotherapy." (PMID 33931967, 2021). "Approximately 15–30% of patients with lung cancer harbor mutations in the EGFR gene." (PMID 33863983, 2021). "It is discovered that activation of the EGFR T790M/L858R mutation in lung epithelial cells can drive lung cancers with alveolar or bronchiolar features, which can originate from alveolar type 2 (AT2) cells or bronchioalveolar stem cells, but not basal cells or club cells of the trachea." (PMID 34622577, 2021). "Similarly, a French study also confirmed this conclusion; the researchers found that the expression of PD-L1 was decreased, and the density of CD8+T lymphocytes was lower in patients with EGFR mutations in lung cancer through IHC." (PMID 34136375, 2021). "In subgroup analysis of stage IB–IIIA tumors with high recurrence rates, 19-del subtype mutations were associated with shorter RFS than that of the exon 21-L858R mutation (p = 0.008), while 19-del in advanced-stage lung cancer has been shown to be a good predictive factor for the use of EGFR-TKIs." (PMID 34298845, 2021). "However, the frequency of EGFR T790M germline mutation in Chinese lung cancer patients was 0.0078%, suggesting a distinct germline mutation spectrum among different ethnicities." (PMID 34869019, 2021). "Furthermore, GSH levels were significantly reduced in lung cancer cells expressing EGFR T790M mutation." (PMID 33808242, 2021). "EGFR is a well-known proto-oncogene, and its hyperactivation via mutation and overexpression has been linked to tumor development and malignancy in various solid tumors, including lung cancer, breast cancer, and colon cancer." (PMID 33440835, 2021). "However, there is a possibility that EGFR mutations cannot be detected in patients with EGFR mutant lung cancer if the amount of cDNA is below the threshold of detection sensitivity." (PMID 33757469, 2021). "TKIs targeting EGFR are used to treat lung cancer patients with EGFR amplification and mutations." (PMID 35070958, 2021). "We have developed a new preclinical mouse model that will help the lung cancer community to develop and test in vivo novel therapeutic options for patients with EGFR-mutated lung cancer who relapse after osimertinib therapy due to the appearance of MET amplification." (PMID 34298655, 2021).
lung cancer (continued). "In our current study, among the lung cancer patients who underwent testing for EGFR mutations, 49.10% had mutations in the younger group, and 44.81% had mutations in the older group; the difference was not significant, which was consistent with a recent study in Chinese patients." (PMID 33767239, 2021). "EGFR mutation-positive lung cancer is a classic example of monoclonal evolution in tumors." (PMID 34831415, 2021). "Therefore, EGFR mutation with CDKN2A (P16) deletion mutation is associated with the development of lung cancer." (PMID 35004697, 2021). "Gene variations that have been identified as conferring higher risk of NSCLC could be either germline or somatic, with some of the most common lung cancer-related driver mutations linked to epidermal growth factor receptor gene (EGFR)." (PMID 32256580, 2020). "The L858R point mutation of EGFR is one of the most frequent oncogenic drivers in lung cancer." (PMID 33096790, 2020). "Analogous to mesenchymal variants of EGFR mutant lung cancer, transformed SCLC variants may possess novel RTK dependencies that can be therapeutically targeted." (PMID 32292420, 2020). "Most patients with lung cancer have tumor-activating EGFR mutations." (PMID 32070026, 2020). "This hypothesis is supported by the evidence that in other human tumors the mutated allele is also amplified (i.e., EGFR in lung cancer)." (PMID 33383911, 2020). "For instance, the rare exon 20 mutation S768I occurs in 1%–2% of EGFR mutation lung cancers." (PMID 32776462, 2020). "In addition, overexpression of HGF is observed in approximately 61% of patients with EGFR-TKIs-resistant lung cancer and is known as a cause of acquired resistance." (PMID 32290402, 2020). "Interestingly, many lung cancer “driver” genes were highly expressed in the rare epithelial cells, with expression of EGFR and KRAS, the top mutated oncogenes in adenocarcinoma, enriched in ionocytes and neuroendocrine cells, respectively." (PMID 32727470, 2020). "Tumors with mutations in the EGFR (11% of lung cancers) may be treated with erlotinib, gefitinib, afatinib or osimertinib." (PMID 32898185, 2020). "EGFR mutation is the most common gene mutation in Asian female lung adenocarcinoma patients, therefore the prognosis of female lung cancer patients might be better." (PMID 32680464, 2020). "Besides the newly acknowledged relevance of STK11 in lung cancer, this disease is characterized by other, well known genetic abnormalities, such as EGFR, BRAFv600E mutations, ALK, ROS, or RET rearrangements, as well as METexon14 mutations." (PMID 32258034, 2020). "In the case of lung cancer, the mutations are often found in the kinase domain, and inhibition of EGFR signaling by means of monoclonal antibodies and small molecule reversible TK inhibitors (TKIs) become a popular approach that was overshadowed by a fast development of resistance." (PMID 32429547, 2020). "In this study, parthenolide could induce apoptosis and growth inhibition in the EGFR mutated lung cancer cells." (PMID 33292235, 2020). "Moreover, in lung cancer, EGFR and MET mutations, oncogene fusions or STK11 inactivating mutations were associated with low response rates." (PMID 32708698, 2020). "The EGFR mutation rate of lung cancer in European and American countries is approximately 15%." (PMID 32191394, 2020). "Therefore, this study aimed to further our understanding of CEA expression in different pathological subtypes in advanced lung cancer patients and to verify the effects of EGFR mutation status on the prognostic potential of CEA in these patients." (PMID 32034239, 2020). "An EGFR mutation causes rapid cell growth, which helps lung cancer spread." (PMID 33178836, 2020).
lung cancer (continued). "Pleural retraction is correlated with lung cancer, and with the EGFR mutation." (PMID 33396348, 2020). "Previous reports of EGFR activating mutations (common mutations) described the frequency of exon 19 deletion mutations as 44.8% (2573/5741) and 39.8% for L858R mutations (2283/5731) in lung cancer." (PMID 32833992, 2020). "To determine whether the CRISPR-Cas12a system could detect circulate EGFR mutations in clinical plasma specimens, we obtained plasma samples of 28 lung cancer patients." (PMID 32093010, 2020). "Besides, CCAT1 sponged miR-218, conquering gefitinib-caused apoptosis of lung cancer cells with EGFR mutant." (PMID 33072561, 2020). "Similar to the EGFR-activating mutations in lung cancer patients, identifying HNSCCs that are sensitive to EGFR-TKI could be a key aspect of the EGFR-TKI treatment response." (PMID 32929368, 2020). "In addition, while the number of cases of lung cancer diagnosed in Kentucky were drawn from a population-based cancer registry, the analysis of erlotinib prescribing and EGFR testing was conducted with a linked insurance claims database." (PMID 32810185, 2020). "This is the first prospective study showing that ctDNA genotyping provides a feasible diagnostic approach for frail lung cancer patients who are unable to undergo biopsy, which subsequently leads to EGFR‐targeted therapy resulting in improved outcomes in a subgroup of patients." (PMID 31991049, 2020). "Since EGFR mutation is relatively common in lung cancer, this mechanism found between prostate cancer cells and hepatocyte may also be used by lung cancer cells, although currently it is not thoroughly studied." (PMID 33262947, 2020). "Our results advanced our understanding of the molecular mechanisms underlying EGFR-TKI resistance and indicated that the miR-506/SHH axis might represent a novel therapeutic target for future EGFR mutated lung cancer treatment." (PMID 33291316, 2020). "Our designed MB-based lung cancer panel covers eight EGFR variants." (PMID 32099048, 2020). "This study aimed to identify an efficient, simple, and specific method of detecting mutations in the epidermal growth factor receptor (EGFR) gene in isolated lung cancer circulating tumor cells (CTCs) and to improve the ability to obtain tumor tissue clinically." (PMID 32856417, 2020). "Furthermore, to explore the effects of TAS-116 on other cancers, we evaluated its effects on EGFR-mutated lung cancer." (PMID 31857719, 2020). "Recently, several studies examined the presence of EGFR mutations in lung cancer by immunohistochemistry (IHC) using the two mutation-specific antibodies employed in the present study and demonstrated sensitivity ranging from 24% to 100% and specificity ranging from 77% to 100%." (PMID 33196648, 2020). "TAS-116 may be effective against tumours resistant to TKIs due to secondary mutations, such as in GISTs or EGFR-mutated lung cancer." (PMID 31857719, 2020). "These discoveries have transformed the outcomes of advanced lung cancer with the development of tyrosine kinase inhibitors (TKI) targeting driver mutations such as EGFR directed TKIs and immune checkpoint inhibitors (ICI) which unleash the host immune system against tumor cells." (PMID 33194687, 2020). "It was also effective against gefitinib-naïve and gefitinib-resistant EGFR-mutated lung cancer." (PMID 31857719, 2020). "It however appears that age independently associates with EGFR mutation among lung cancer." (PMID 32850378, 2020). "The functional crosstalk between GPCRs and EGFR linked to EMT could be a potential target for inhibiting EMT-associated metastasis in lung cancer." (PMID 33050301, 2020).